DUX4 (double homeobox 4)
Diseases named in the same sentence as DUX4 in open-access papers (continued):
Sharing a sentence is not in itself a finding about the gene and the disease.
infection (continued). "HSV-1 infection also triggered the expression of DUX4 and SLC34A2 in SH-SY5Y neuroblastoma cells, a neuron infection model frequently used to study HSV-1 infection." (PMID 41211819, 2025). "Upon infection with HSV-1, however, transcription of DUX4 is induced as well as known DUX4 target genes." (PMID 39814710, 2025). "DUX4 is functionally required for infection, since genetic depletion by CRISPR/Cas9 as well as degradation of DUX4 by nanobody constructs abrogates HSV-1 replication." (PMID 39814710, 2025). "Taken together, this confirms that ICP0 and ICP4 are necessary and sufficient for inducing DUX4 expression and indicates that DUX4 is only briefly activated by ICP0 and ICP4 during the early phase of infection." (PMID 39814710, 2025). "Western Blot as well as qRT-PCR experiments further confirmed the expression of DUX4 and known DUX4-target genes TRIM48, TRIM49, ZSCAN4, ZSCAN5a, ZSCAN5d and RFPL4A upon HSV-1, HCMV and KSHV-infection 25 in different experimental settings." (PMID 38168299, 2023). "DUX4 expression was also induced upon infection of primary human melanocytes with HSV-1, emphasizing the physiological relevance of DUX4 induction." (PMID 38168299, 2023). "This indicates that DUX4 is only briefly activated by ICP0 and ICP4 during the early phase of infection." (PMID 38168299, 2023). "Upon infection with HSV-1, however, transcription is induced for DUX4 as well as known DUX4 target genes." (PMID 38168299, 2023). "Next, we wanted to address the significance of herpesviral DUX4 induction for the infection itself, since DUX4 is a germline transcription factor that is not expressed in healthy adult tissue." (PMID 39814710, 2025). "To elucidate the involvement of HSV-1 tegument proteins in the induction of DUX4 expression we performed infection experiments with HSV-1 mutants lacking the immediate early proteins ICP0, ICP4 and ICP34.5." (PMID 39814710, 2025). "Whereas the expression of early and late genes is higher in wt cells at 8 h post infection, the expression of immediate-early genes like UL54 or US1 is lower in the wt and higher in the ko cells, indicating that DUX4 is required for progression to the later stages of HSV-1 infection." (PMID 39814710, 2025). "Blocking viral DNA replication with PAA results in higher levels of DUX4 and its target genes, suggesting DUX4 behaves similarly to the strong HSV-1 beta genes, which are upregulated early in infection and are shut down during the switch to viral DNA replication and late gene expression." (PMID 38168299, 2023). "DUX4 for example is not expressed in healthy adult tissue, but highly upregulated upon infection with human herpesviruses." (PMID 37876935, 2023). "Next, we wanted to address the significance of herpesviral DUX4 induction for the infection itself, since DUX4 is a germline transcription factor that is not expressed in healthy adult tissue 8,10." (PMID 38168299, 2023). "Whereas the expression of early and late genes is higher in wildtype cells at 8h post infection, the expression of immediate-early genes like UL54 or US1 is lower in the wildtype and higher in the knockout cells, indicating that DUX4 is required for the later stages of HSV-1 infection." (PMID 38168299, 2023). "Genes repressed by DUX4 induction are significantly enriched in the set of genes transcriptionally downregulated during HSV infection, further identifying DUX4 and possibly other embryonic transcription factors as master regulators during infection." (PMID 34578417, 2021). "By co-staining of cells with a DUX4 antibody, we could demonstrate that only ICP4+/VP26− cells (YFP+/RFP− cells) show nuclear expression of DUX4, indicating activation of DUX4 within early stages of infection." (PMID 38168299, 2023). "Upon infection of HAP1 DUX4 knockout (ko) cells, we could not detect a DUX4 specific band in the Western Blot, which is present in the infected wildtype (wt) HAP1 cells." (PMID 38168299, 2023).
infection (continued). "Human adenovirus (HAdV) and vaccinia virus (VACV) infections could not induce DUX4 expression." (PMID 41211819, 2025). "Upon infection of HAP1 DUX4 knockout (ko) cells, we could not detect DUX4 protein by Western Blot, while as expected it is present in the infected wildtype (wt) HAP1 cells." (PMID 39814710, 2025).
genetic disease (5 papers, 2018 to 2023). "FSHD is a dominant genetic disease with a critical epigenetic component resulting in mis-expression of the cytotoxic isoform of the old-world primate DUX4 gene." (PMID 29415061, 2018).
CNS tumors (2 papers, 2024 to 2025). "Whereas a CIC::DUX4 fusion is encountered in 95% of SARC‐CIC of the soft tissues, the molecular spectrum of CNS tumors seems to be broader with different fusion partners (NUTM1, LEUTX, DUX4) which may or may not include the gene CIC." (PMID 39442927, 2025).
genetic muscle disease (2 papers, 2020 to 2025). "FSHD is a genetic muscle disorder caused by the loss of transcriptional repression of DUX4 gene, resulting in its aberrant expression and subsequent progressive muscle wasting predominantly in the face, shoulder blades and upper arms." (PMID 32883366, 2020).
hematological malignancies (2 papers, 2019 to 2025). "This allowed us to identify novel SNVs in genes previously reported as mutated in ALL or other hematological malignancies: CREBBP, CSF3R and DUX4." (PMID 41333018, 2025).
muscular disorder (2 papers, 2022 to 2024). "FSHD is a muscular disorder strongly associated with an aberrant expression of the DUX4 gene." (PMID 35621301, 2022). "In the absence of TMX, TIC-DUX4 mice showed a low level of DUX4 expression only when old (>1.5 years), while TMX-treated TIC-DUX4 mice developed the typical histological and functional phenotype of an FSHD-like muscular disorder." (PMID 38607035, 2024).
autosomal dominant disease (1 paper, 2019). Autosomal dominant form of disease. "Facial-scapular-humeral myodystrophy Landouzy-Dejerine (FSHD) is an autosomal dominant disease, the basis of its pathogenesis is ectopic expression of the transcription factor DUX4 in skeletal muscle." (PMID 30871534, 2019).
DUX4 also shares sentences with these, for which no sentence is quoted: alveolar rhabdomyosarcoma (3 papers); progressive muscular dystrophy (3); synovial sarcoma (3); alveolar soft part sarcoma (2); clear cell sarcoma (2); skeletal muscle disorder (2); acute myeloid leukemia (1); alopecia (1); Alzheimer disease (1); Anosmia (1); ataxia syndrome (1); atherosclerosis (1); basal cell carcinoma (1); Bosma Arhinia and Microphthalmia syndrome (1); brain cancer (1); brain injury (1); cardiac hypertrophy (1); cervical carcinoma (1); CNS sarcoma (1); Coats disease (1); colorectal cancer (1); dermatofibrosarcoma protuberans (1); desmoplastic small round cell tumor (1); diabetic retinopathy (1); Down syndrome (1); Ewing family tumors (1); experimental autoimmune encephalomyelitis (1); fibromuscular dysplasia (1); fibrosis (1); glioblastoma (1).
A further 33 diseases each share a sentence with DUX4 in 1 paper.